RNU6-670P (RNA, U6 small nuclear 670, pseudogene)
Gene: Small nuclear RNA gene on chromosome 3 (10,037,552 to 10,037,655, forward strand). Ensembl gene ENSG00000201182.
Homologues: Orthologues: chimpanzee U6 (99% identical), macaque U6 (93% identical), rabbit U6 (88% identical). Paralogues in human: RNU6-16P (88% identical), RNU6-39P (88% identical), RNU6-45P (88% identical), RNU6-59P (88% identical), RNU6-12P (87% identical), RNU6-13P (87% identical), RNU6-32P (87% identical), RNU6-7 (87% identical), RNU6-8 (87% identical), RNU6-1 (86% identical), RNU6-1029P (86% identical), RNU6-1297P (86% identical), and 1287 more.